ACE (angiotensin I converting enzyme)
Diseases named in the same sentence as ACE in open-access papers (continued):
Sharing a sentence is not in itself a finding about the gene and the disease.
Hypertension (continued). "These concerns were primarily based on findings that ACE inhibitors (ACEi) or angiotensin II type 1 receptor (ARB) upregulate the expression and activity of ACE2, the SARS-CoV-2 receptor, in the kidneys and heart of experimental models of hypertension." (PMID 33329052, 2020). "For example, an intervention proposal was made to the prescriber (code I1.3) if a patient seemed to suffer from T2DM and hypertension, but received no angiotensinconverting enzyme inhibitor (ACE inhibitor) or angiotensin II receptor blockers (ARB)." (PMID 32903568, 2020). "Angiotensin-I converting enzyme (ACE) is a zinc-containing metalloproteinase that catalyzes the conversion of angiotensin I to angiotensin II, a potent vasoconstrictor involved in the pathogenesis of hypertension." (PMID 33007997, 2020). "Patients with severe COVID-19 and diabetes or hypertension as comorbidities were advised not be treated with ACE inhibitors or angiotensin IIAT1 receptor inhibitors because a potential upregulation of ACE2 would facilitate and worsen SARS-CoV-2 infection." (PMID 32719619, 2020). "The important role of angiotensin I-converting enzyme (ACE) in increasing blood pressure has been demonstrated in the past decades, as about 9.4 million patients die from hypertension worldwide every year and 1.6 billion people are suffering from high blood pressure." (PMID 32121212, 2020). "On the other hand, not all animal venoms induce hypertension, with some snake, spider and scorpion venoms instead inducing hypotensive shock due to the presence of ACE-inhibiting bradykinin-potentiating peptides (BPPs)." (PMID 33146371, 2020). "We performed a multivariate logistic analysis and found that BMI, hypertension and CRP were dependent risk factors for the severity of COVID-19, while serum ACE activity was not." (PMID 33238910, 2020). "Renin-angiotensin-aldosterone system (RAAS) inhibitors, which include angiotensin-converting enzyme (ACE) inhibitors (ACEIs) and angiotensin II receptor type 1 blockers (ARBs) are widely used for treatment of hypertension, heart failure and coronary heart disease." (PMID 33178900, 2020). "Based on our result, we infer that add-on therapy in patients with essential hypertension not controlled with monotherapy of ACE inhibitor/ARB can be initiated with either a TD or a CCB without significant difference in regression of LVH." (PMID 33102689, 2020). "ACE inhibitors reduce the level of oxidative stress (H2O2, malondialdehyde (MDA), and reactive oxygen species (ROS) formation) and increase anti-oxidative activity in rats with hyperglycemia, diabetes, hepatic fibrosis, and hypertension." (PMID 31590451, 2019). "In adults with hypertension and chronic kidney disease, treatment with an ACE inhibitor or ARB when ACE inhibitors are not well tolerated is indicated to delay the progression of renal disease." (PMID 31337127, 2019). "In female rats, a low level of ACE protein did not affect the blood pressure, but male rats were protected from hypertension." (PMID 30333281, 2019). "Beta-blockers and angiotensin-converting enzyme (ACE) inhibitors, commonly used to treat congestive heart failure and hypertension, may in fact contribute to aggravate the impairment of compensatory mechanisms typical of the elderly." (PMID 31717303, 2019). "However, in the late cohort, more patients were treated with ACE-inhibitors/angiotensin receptor blockers, calcium channel blockers and oral anticoagulants, which could suggest an overall better management of hypertension, heart failure and atrial fibrillation." (PMID 30832574, 2019). "Although no randomized-controlled trials have been performed, angiotensin converting enzyme (ACE) inhibitors are commonly prescribed for the treatment of hypertension and/or renal disease in SLE patients." (PMID 30712132, 2019).
Hypertension (continued). "Our previous study has not shown the different alleles of the ACE and AGT genes to have any significant influence on the incidence and course of COPD, hypertension, or a combination of the two." (PMID 32025262, 2019). "It has been suggested that antihypertensive medication, especially angiotensin-converting enzyme (ACE) inhibitors, may regress myocardial fibrotic remodeling in response to hypertension." (PMID 31604432, 2019). "Only two other studies, conducted in different ethnic groups of the Chinese population, addressed ACE and ACE2 polymorphisms together in susceptibility to hypertension, but none of them explored the interaction or combination between the two genes." (PMID 31430320, 2019). "For example, ACE inhibitors demonstrate very significant prolonged positive effects in all animal models of hypertension, without exclusion." (PMID 31112562, 2019). "Moreover, the combination of garlic and its bioactive compound alliin and captopril increased the activity of captopril on inhibiting angiotensin-converting enzyme (ACE) and hypertension in rats." (PMID 31284512, 2019). "Patients in the T2DKD, T2DNRF and CCKD groups were prescribed medications such as angiotensin converting enzyme (ACE) inhibitors or angiotensin II receptor blockers (ARBs), statins, oral hypoglycaemic drugs and/or insulin to manage hypertension, dyslipidaemia and diabetes respectively." (PMID 31358876, 2019). "If fimasartan is not inferior to an ACE inhibitor that has been proven effective and safe, the drug will be considered as an option in the treatment of hypertension in elderly patients." (PMID 31262348, 2019). "Knockout models of renal ACE, have demonstrated the absence of hypertension in response to chronic Ang II infusions." (PMID 31680980, 2019). "In this regard, the RAS is strongly involved in blood pressure regulation and cardiovascular disease programming; hence, the overexpression of ACE and AT1R in the lung may induce hypertension." (PMID 30691489, 2019). "The evaluation of aSRs among ACE inhibitor and ARB initiators helped quantify the influence of natural disease progression that may warrant the use of a loop diuretic for hypertension control." (PMID 31880802, 2019). "First, in the updated United States and European ACS guidelines, ACE inhibitors/ARBs received a class I recommendation only for ACS patients with heart failure, hypertension, or diabetes, and beta-blockers received a class I recommendation only for ACS patients with heart failure." (PMID 31170175, 2019). "We did not observe any significant correlations between ACE and AGT gene polymorphisms and parameters of oxidative stress in a setting of comorbid COPD and hypertension." (PMID 32025262, 2019). "We suggest using ACE inhibitors or angiotensin receptor blockers as first-line antihypertensive treatment in children with ADPKD who have hypertension without albuminuria (evidence level C; recommendation level moderate)." (PMID 31118499, 2019). "However, given that activation of the RAAS is still likely to be a major contributor to hypertension in children with ADPKD, we support the use of ACE inhibitors and angiotensin receptor blockers as the first-line anti-hypertensive agent in this population." (PMID 31243534, 2019). "Angiotensin-converting enzyme (ACE) inhibitors, angiotensin II receptor blockers (ARBs), calcium channel blockers, and diuretics are recommended as first-line treatments for essential hypertension in elderly individuals without comorbidities." (PMID 31262348, 2019). "Among those with elevated blood pressure but no hypertension diagnosis, β-blockers (13.1%), ACE inhibitors (9.7%), and calcium channel blockers (9.5%) were the most commonly prescribed antihypertensive medications." (PMID 29494332, 2018). "Angiotensin-converting enzyme (ACE) plays a critical role in blood pressure control systems (renin-angiotensin system) as it converts angiotensin I into angiotensin II, leading to the development of hypertension." (PMID 30081563, 2018).
Hypertension (continued). "While increased plasma renin activity was reported by several laboratories, and local ACE activity was stimulated in the LV and aorta, serum ACE activity was not increased in l-NAME-induced hypertension." (PMID 29382124, 2018). "Guidelines recommended ARB and ACE inhibitors were underutilized in treating hypertension with LVH and renal disease, while guidelines discouraged BB were prescribed to the patients with uncomplicated hypertension." (PMID 29721335, 2018). "Several synthetic ACE inhibitory (ACEI) agents, such as captopril, lisinopril, and enalapril, have been commonly used as drugs to treat hypertension, though sometimes accompanied with side effects, such as proteinuria, cough, allergic skin rashes, and altered sense of taste." (PMID 30453595, 2018). "As a result, there is a great demand for safer and more compatible natural ACE inhibitors for treating hypertension in a nontoxic manner." (PMID 29854760, 2018). "Beneficial heart failure and hypertension medications such as ACE-inhibitors and ARBs are usually not stopped for electrophysiology/ablation procedures, as the individual would invariably be taking them long-term to treat their chronic condition." (PMID 28883795, 2017). "However, the proportion of patients exposed to an ACE inhibitor or an ARA2 drug was 54%, which seems rather low given the number of subjects with hypertension (88.4%)." (PMID 28143424, 2017). "It is a more potent and effective ACE inhibitor than EPL and is also effectively used in the treatment of hypertension and congestive heart failure through dilation of peripheral vascular resistance without causing any significant changes in heart rate or cardiac output." (PMID 28344828, 2017). "Angiotensin-I-converting enzyme inhibitors—which can reduce the activity of the angiotensin-I-converting enzyme (ACE)—have an antihypertensive effect in vivo, and play a key role in the treatment of the hypertension." (PMID 28212269, 2017). "Thus, angiotensin-converting enzyme (ACE) inhibitors (which block the conversion of AngI to AngII) and AT1R blockers are widely used for the treatment of hypertension and atherosclerotic CVD4." (PMID 29133788, 2017). "Nowadays, the angiotensin converting enzyme (ACE) inhibitors (e.g., Capoten (captopril), Vasotec (enalapril), Prinivil, or Zestril (lisinopril), etc.)have been considered as first-line drugs for the treatment of hypertension and myocardial infarction." (PMID 29099799, 2017). "It is an angiotensin-converting enzyme (ACE) inhibitor, used for oral treatment of hypertension." (PMID 28894622, 2017). "The ET-1 concentration and the ACE activity dependent, in this study on gender, hypertension, smoking,obesity and dyslipidemia, unlike diabetes, Personal cardiovascular antecedents, alcohol and physical inactivity." (PMID 27894250, 2016). "Interestingly, the pathology of stroke co-morbidities such as hypertension and gender are all influenced by RAS dysfunction, where there is an increased/overactive ACE/Ang II/AT1R pathway." (PMID 27761230, 2016). "An additional 10% of patients had started RAS inhibitors (7 ACE-inhibitors and 3 angiotensin receptor blockers; 2 with T2D, and 8 with hypertension without T2D; p = NS)." (PMID 27649410, 2016). "So, there is a dire need to find natural ACE inhibitors with lower or no side effect in order to development pharmaceuticals and nutraceuticals for the prevention and remedy of hypertension." (PMID 27271639, 2016). "In the present cohort study of ACEI-treated patients with CHF, we examined the prognostic value of two distinct pharmacogenetic scores A and B that have previously been found to influence ACEI efficacy and ACE activity in patients with stable IHD and hypertension, respectively." (PMID 26633885, 2015). "These objectives were achieved by determining and comparing the genotypic frequencies of ACE gene I/D polymorphism in obese and nonobese T2DM and hypertension patients." (PMID 26491214, 2015).
Hypertension (continued). "Although the ACE inhibitory potencies of these peptides are not as great as the ACE inhibitor drugs commonly used for treatment of hypertension, they are naturally derived from food protein sources." (PMID 26184305, 2015). "The limitations of our study include the smaller sample size in the obese and nonobese subgroups created to study the association of ACE DD genotype with T2DM and hypertension." (PMID 26491214, 2015). "Interestingly, in spite of developing arterial hypertension, renal expressions of key renal RAS components leading to an overproduction of Ang II (ACE) and responsible for its harming effect (AT1 receptors) has been suppressed in our SHRs." (PMID 25766467, 2015). "Under non-homeostatic or disease conditions, these catalytic actions of ACE can result in blood vessel wall stiffening and inability to relax following contraction, which, if not controlled, leads to hypertension." (PMID 26715103, 2015). "The ACE/Ang II signaling mediates various miRNAs expression via the activation of AT1R and these miRNAs, thereby contributing to VSMCs proliferation, cardiovascular remodeling, and hypertension." (PMID 25815211, 2015). "It has also been suggested that all ACE inhibitors do not prevent dementia in older adults being treated for hypertension but centrally acting ACEIs such as ramipril or perindopril do appear to reduce cognitive decline in older adults." (PMID 26300914, 2015). "Renin angiotensin system blockers, ACE inhibitors (ACEI) and angiotensin receptor blockers (ARB) have been broadly used to treat congestive heart failure, hypertension, proteinuria and chronic kidney disease, and additionally play a significant role in improving dyslipidemia." (PMID 26291618, 2015). "The rise in serum ACE activity due to hypertension can be ruled out as the blood pressure measurement of workers revealed normo-tension." (PMID 27275272, 2015). "We planned this study with a large and a very well defined population to evaluate the association of ACE polymorphism with T2DM and hypertension in the presence and absence of obesity." (PMID 26491214, 2015). "Inhibition of ACE is considered a useful therapeutic approach in the management of hypertension in both diabetic and nondiabetic patients." (PMID 26788368, 2015). "A number of these variables were correlated: diabetes, hypertension and use of diuretics, beta-blockers and ACE inhibitors and thus not independently explanatory." (PMID 24670976, 2014). "This mutation affected at least eight families, but there were no ACE-related clinical abnormalities or hypertension." (PMID 24690767, 2014). "A gender-dependent effect analysis showed the strongest association between the ACE I/D polymorphisms and CKD risk in Asian males with hypertension (OR: 3.75; 95% CI: 1.84–7.65) or without (OR: 2.42; 95% CI: 1.40–4.20)." (PMID 24498151, 2014). "Other medications such as beta-receptor blockers, angiotensin-converting enzyme (ACE) inhibitor or angiotensin receptor blocker, and medications for hypertension or glucose control were prescribed accordingly, and no between-group differences were found." (PMID 24580749, 2014). "This mutation affected at least eight families, but again, there were no ACE-related clinical abnormalities or hypertension." (PMID 24691160, 2014). "Concerning the role of the local renal RAS on the generation of hypertension, recent studies revealed that the infusion of Ang II into mice lacking renal ACE, indicated no renal responses or hypertension in the knockout mice compared with wild-type control." (PMID 24600438, 2014). "Males had higher OR for the association between ACE I/D polymorphisms and CKD risk than females in Asians but not Caucasians, regardless of adjustment for hypertension (p<0.05)." (PMID 24498151, 2014). "This can be explained by the fact that the guidelines recommend not to combine ACE inhibitors with ARBs for the treatment of hypertension." (PMID 24685255, 2014).
Hypertension (continued). "Therefore, the renin-angiotensin system inhibitors, including ACE inhibitors and AT-1R blockers (ARB), are used widely for the treatment of hypertension." (PMID 24959250, 2014). "Therefore, new inhibitors are being developed to target ACE and particularly to have antioxidant activity; so in concert the new properties of one inhibitor may contribute to endothelium-dependent protective effects against oxidative stress and high blood pressure." (PMID 24804145, 2014). "In contrast, angiotensin-converting enzyme (ACE) inhibitors, widely used to treat high blood pressure by interfering with the renin-angiotensin system, did not affect CXCR4 expression on primary human monocytes and THP1 cells." (PMID 24966838, 2014). "Based on the downregulation of AVPR1B and ACE and the upregulation of DRD5, DG treatment may be involved in the rennin-angiotensin system and the receptor-mediated improvement of hypertension." (PMID 24174980, 2013). "The usage of ACE inhibitors, α-blockers, β-blockers, furosemide, spiranolactone and thiazide diuretics were significantly more in the resistant hypertension group than in the non-resistant hypertension group." (PMID 24053215, 2013). "Links between the lack of the ACE Alu insertion and hypertension, as well as other diseases, have been reported." (PMID 23717661, 2013). "Ang II, the fundamental determinant in the renin-angiotensin system is formed by the action of angiotensin converting enzyme (ACE) on angiotensin I, and is a crucial factor in the etiology of hypertension and resultant changes in cardiac morphology and remodeling." (PMID 24077237, 2013). "However, the degree of association between hypertension and other tag-SNPs was much lower and not statistically significant and the magnitude of the association between the CC genotype in rs1800764 and hypertension was moderate compared to that with ACE activity." (PMID 23469169, 2013). "It has been suggested that the increase in serum ACE activity in essential hypertension is not of pathophysiological or clinical significance." (PMID 24098401, 2013). "Around half of the patients had been treated with ACE inhibitors/angiotensin receptor blockers (most of them for hypertension), without significant differences between both registries." (PMID 22708978, 2012). "Several clinical trials have documented beneficial effects of ACE inhibitors and ARBs on cardiovascular end-points in type II diabetic and metabolic syndrome patients without hypertension." (PMID 22829804, 2012). "Although the blockade of RAS by ACE-Is or ARBs (RAS inhibitors) may be effective, the long-term treatment of hypertension by drugs classified as such often results in a diminished efficacy owing to the inadequate suppression of aldosterone synthesis." (PMID 23097668, 2012). "It has been reported that suppression of the renin-angiotensin system (RAS) by angiotensin-converting enzyme inhibitors (ACE-Is) and angiotensin II type 1 receptor blockers (ARBs) provides an effective treatment against cardiovascular diseases such as hypertension and cardiac failure." (PMID 23097668, 2012). "Diverse antihypertensive drugs are available to treat high blood pressure and clinical trials evidenced the benefit of inhibitors of RAS, i.e. ACE inhibitors and AGTR blockers for the prevention of cardiovascular diseases in the general population as well as in transplant recipients." (PMID 21298017, 2011). "Thus the antihypertensive effect of fermented milk cannot be explained alone by the ACE inhibitory activity of IPP and VPP, contrary to the earlier findings on a less severe hypertension model, SHR." (PMID 20721338, 2010). "Although the phenomenon of ACE escape represents a drawback for the ACEI drug class in the treatment of hypertension, the ARB class is not without its own shortcomings." (PMID 21994809, 2010).